RNU6-698P (RNA, U6 small nuclear 698, pseudogene)
Gene: Small nuclear RNA gene on chromosome 19 (53,653,685 to 53,653,791, forward strand). Ensembl gene ENSG00000200393.
Homologues: Orthologues: chimpanzee U6 (97% identical). Paralogues in human: RNU6-1316P (94% identical), RNU6-25P (94% identical), RNU6-33P (94% identical), RNU6-34P (94% identical), RNU6-38P (94% identical), RNU6-7 (94% identical), RNU6-8 (94% identical), RNU6-891P (94% identical), RNU6-1 (93% identical), RNU6-116P (93% identical), RNU6-2 (93% identical), RNU6-20P (93% identical), and 1287 more.